CD4 (CD4 molecule)
Diseases named in the same sentence as CD4 in open-access papers (continued):
Sharing a sentence is not in itself a finding about the gene and the disease.
lymph node metastasis (79 papers, 1994 to 2026). "A decrease in the number of CD8+ T cells, an increase in Foxp3+ Tregs, and an increased ratio of Foxp3+ Treg/CD4+ T cells are significantly associated with lymph node metastasis and prognosis." (PMID 40106761, 2025). "Serum CD4 was found to be associated with the Borrmann classification and lymph node metastasis, while serum CD4 and CD19 were associated with age." (PMID 34258299, 2021). "Instead, the magnitudes of the increase in the proportion of CD8+ T cells and the decrease in the proportion of CD4+ T cells after CRT termination were significantly associated with residual lymph node metastasis." (PMID 29765096, 2018). "In contrast, the higher frequency of TIM-3+CD4+ TILs showed significant association with lymph node metastasis and more advanced cancer stages." (PMID 22363469, 2012). "Notably, TIM-3 expression on CD4+ T cells has been linked to lymph node metastasis and advanced disease stages." (PMID 40724985, 2025). "Moreover, CD4+ Tm cell and CD4+ T cell levels are significantly associated with lymph node metastasis in patients with LCC and RCC." (PMID 29230377, 2017). "In addition, as for CD47 alone, CD4–MET co-expression was strongly associated with lymph node metastasis (Cochran-Armitage test for trends, p=0.04): 5/7 (71.4%) patients had lymph node metastases in the MET-CD47 double positive group versus 51/143 (35.7%) in the CD47-MET double negative group." (PMID 25230070, 2014). "CD3+CD4+ T lymphocytes were correlated with positive extensive intraductal components, nodal stage N2 cancer, and positive extranodal extension of lymph node metastasis." (PMID 39749673, 2025). "To investigate the potential role of CD4+ Tregs in lymph node metastases, we identified the upregulated genes in CD4+ Tregs from metastatic lymph nodes, including IFI27, IL2RA and IL2RB." (PMID 39741182, 2025). "Studies have shown that a lower CD4+/CD8+ ratio corresponds to less lymph node involvement, while increased CD8+ T cell expression is associated with a reduction in lymph node metastasis and better overall survival in TNBC." (PMID 39769460, 2024). "Our findings indicated that SEC61G is positively correlated with lymph node metastasis but negatively correlated with B cells, CD4+ T cells, macrophages, and dendritic cells." (PMID 38978503, 2024). "CD4+CD25+FOXP3+ Treg infiltration was correlated with lymph node metastasis (p = 0.047), stage (p = 0.017), and lymphatic invasion (p = 0.004)." (PMID 39264227, 2024). "The most remarkable result is that CD4+ T cells decreased in both primary foci and lymph node metastases, which was contrary to the results from those three online analyses, which indicated an increase in CD4+ T cells." (PMID 37162299, 2023). "Our findings revealed that the increased PD1 of CD4+ T cells in LN+ was related to lymph node metastasis progression." (PMID 37270478, 2023). "The study findings indicate that the levels of ITGA2, CD4, and CD8 in tumor tissues are significantly associated with histological grade, TNM stage, lymph node metastasis, and local invasion (P < 0.05)." (PMID 37881431, 2023). "The results revealed that histological grade, TNM stage, lymph node metastasis, local invasion, and the expression of ITGA2, CD4, and CD8 in tumor tissues were all associated with patient prognosis." (PMID 37881431, 2023). "T cells infiltrate CC tumors, but the CD4+: CD8+ differs from that in the peripheral blood and lower CD4/CD8 ratios are associated with faster tumor growth and lymph-node metastasis." (PMID 37508372, 2023). "The frequency of circulating peripheral blood terminally differentiated effector memory CD8+ cells (r = − 0.86, p = 0.01) and CD4+ cells (r = − 0.85, p = 0.03) negatively correlated with lymph node metastasis in the treatment-naïve setting." (PMID 35986757, 2023). "On the other hand, in this study, elevated levels of CD3+ and CD4+ lymphocytes were identified in patients with lymph node metastases." (PMID 35206956, 2022).
lymph node metastasis (continued). "Nonetheless, CD4+FoxP3+ Tregs constituted 12%–36% of CD4+ T cells and positively correlated with the presence of lymph node metastases." (PMID 35992118, 2022). "For instance, in our study patients with lymph node metastases had higher infiltration of CD4+TILs in CT." (PMID 36319566, 2022). "We found that patients with lymph node metastasis had higher infiltration rates of type 1 T helper cells, central memory CD4+ T cells, γδ T cells, and natural killer T cell (p = .0442.0479.0353, and .0370, respectively)." (PMID 35433680, 2022). "Our results demonstrated that the expression of VISTA on CD4+ T cells was correlated with lymph node metastasis and poor prognosis in NSCLC patients." (PMID 35122478, 2022). "When the proportion of CD4+ T cells was higher than that of CD8 + T cells, it indicated that the cancer already had lymph node metastasis associated with immune infiltration." (PMID 36185274, 2022). "HLA class II on TILs was negatively associated with lymph node metastasis and positively correlated with programmed death-ligand 1 (PD-L1) on TILs (p<0.001) and multiple immune markers (CD3, CD4, CD8, FOXP3; p<0.001)." (PMID 34362829, 2021). "Increased level of tumor-infiltrating regulatory CD4+CD25+ T lymphocytes was related with lymph node metastasis among BC patients." (PMID 26462021, 2015). "In patients with papillary thyroid cancer CD4+ T cell frequencies correlate with tumour size while Treg frequencies correlate with lymph node metastasis." (PMID 24957270, 2014). "The higher percentage of infiltrating CD4+ T-cells was observed in animals with the worse prognosis, including those with lymph node metastasis and lower survival in days." (PMID 20525350, 2010). "Univariate analysis revealed that tumor depth, lymph node metastasis, stage, lymphatic invasion, venous invasion, infiltration of CD8 and FOXP3, PD‐L1 TC, CD25, CD4+CD25+FOXP3+ Tregs, and the CD8+ TILs/CD4+CD25+FOXP3+ Tregs ratio were significantly associated with OS." (PMID 39264227, 2024). "Our findings revealed that the recruitment of CD4+CD25+FOXP3+ Tregs at the tumor site was associated with an advanced‐stage and lymph node metastasis, and up to 70.9% of patients with high CD4+CD25+FOXP3+ Tregs infiltration showed lymph node metastasis." (PMID 39264227, 2024). "However, CD8 positive T cell expression was significantly decreased in the lymph node metastasis group, indicating that CD4 positive T cell infiltration was significantly increased." (PMID 37254049, 2023). "In summary, our study suggests that lymph node metastasis and recurrence in OSCC are associated with increases in PD1 and glycolysis in CD4+ T cells; Hk2 may be a key enzyme in glycolysis contributing to the progression of metastatic lymph nodes in OSCC." (PMID 37270478, 2023). "CD4+ expression was associated with tongue tumors, no lymph node metastasis (N0, p=0.019) and no LVI (p=0.006)." (PMID 35957892, 2022). "Similarly, in both species, the infiltration of CD4+ T-cells that impose immunosuppressive behavior within the TME is associated with poorer overall survival and risk of lymph node metastasis." (PMID 36291791, 2022). "CD4+ TIL infiltration was seen in a higher proportion of those dogs with lymph node metastasis." (PMID 36291791, 2022). "In addition, we found that the CCR5+/CD4+ ratio was higher in the axillary lymph node metastasis group (0.23 ± 0.07 vs. 0.16 ± 0.03, P < 0.001)." (PMID 36033472, 2022). "Infiltration of CD4+TILs was higher in CT of patients with lymph node metastasis (p = 0.015)." (PMID 36319566, 2022). "Moreover, CD8+T cells, memory activated CD4+T cells, resting NK cells and resting mast cells exhibited a significantly difference in evaluating lymph node metastasis." (PMID 34249930, 2021).
lymph node metastasis (continued). "Interestingly, in biopsies of patients with lymph node metastases (left) or patients who retrospectively developed relapse (right), more CD4+ or IL‐17+ cells represent Th17 cells in comparison with patients without metastases or relapse." (PMID 34469022, 2021). "A trend toward decreased CD4+ T‐cells counts was noted for patients with advancing stage, lymph node metastasis, and distant metastasis, which may imply advancing cancer had escaped immune surveillance and decreased antitumor response." (PMID 32459060, 2020). "There was a decrease in the lymph node metastasis‐related trend of CD4+ T‐cell counts (F = 3.537, P = .004), but an increased lymph node metastasis‐related trend of CD8+ HLA‐DR/ CD8+ T‐cell percentages (F = 4.247, P = .001) and CD8+ CD38+/CD8+ T cells (F = 10.984, P < .001)." (PMID 32459060, 2020). "High infiltration of CD3+and CD8+ cells in IM and CT as well as high CD4+ cell infiltrates in the IM was significantly associated with the absence of lymph node metastases." (PMID 33211709, 2020). "Our results showed that circulating CD4+ Tm cells and CD4+ T cells might be indicators for lymph node metastasis, so that a liquid biopsy before surgery may provide useful node staging information for clinicians to make treatment decisions." (PMID 29230377, 2017). "Furthermore, six parameters of the patients (sex, smoking status, with or without COPD, TNM staging, lymph node metastasis status, and pathological type of tumour) and their association with the CD4+CD25+FOXP3+ Treg percentage were evaluated." (PMID 28253320, 2017). "CD8+ TILs/CD4+CD25+FOXP3+ Treg ratio was significantly correlated with T1 + 2 (28/57, 49.1%), lymph node metastasis (26/49, 53.1%), Stage I + II (29/61, 47.5%), and venous invasion (16/28, 57.1%)." (PMID 39264227, 2024). "Patients without lymph node metastases (N0) had significant enrichment of TIL subpopulations compared to patients with lymph node metastasis (N+) in CD3+, CD8+, CD4+, and CD45RO+ cells." (PMID 35455743, 2022). "CD4 and CD8 positive rate in lymph node metastasis were significantly correlated with that in primary lesions (CD4, p = 0.004; CD8, p = 0.044)." (PMID 34907653, 2022). "With progression in differentiation type and lymph node metastasis, the amount of CD3+ T cells, CD4+ T cells, and CD8+ T cells gradually increased." (PMID 33995627, 2021). "It’s worth noting that the infiltrating levels of resting mast cells were significantly higher and CD8+T cells, memory activated CD4+T cells, resting NK cells were lower in PTME with lymph node metastasis." (PMID 34249930, 2021). "Significant variables in the univariate logistic regression (lymph node metastasis, PD-1 on TILs, PD-L1 on TILs, CD3, CD4, CD8, and FOXP3) were enrolled into the multivariate logistic regression model." (PMID 34362829, 2021). "The lower levels of CD4 (P = 0.024) and CD19 (P = 0.020) were more common in patients younger than 70 years, and higher Borrmann type and lymph node metastasis were related to increased serum CD4 (P = 0.041, P = 0.026)." (PMID 34258299, 2021). "T cell CD4 memory resting, T cell CD8, NK cell resting decreased as the increase of UICC stage and lymph node metastasis, which indicated that the four cells are vital in immune infiltration as well as BCa immunotherapy." (PMID 32579540, 2020). "The increasing CD4+CD25+FOXP3+ Treg percentage was also closely in accordance with the TNM staging and lymph node metastasis status, which is consistent with previous studies." (PMID 28253320, 2017). "Type 1 primarily consisted of patients with negative lymph node metastasis (NM), characterized by immune cells such as NK cells, CD4 T effector memory cells, and memory B cells." (PMID 39507532, 2024). "Furthermore, we observed varying degrees of differences in the expression of CD3+T cells, CD4+T cells, CD8+T cells, CD4+/CD8+ ratio, and LMR in lymph node metastasis, clinical staging, molecular typing, Ki-67 level (P < 0.05)." (PMID 38263363, 2024).
lymph node metastasis (continued). "Additionally, TNFSF10's expression was lower in CD4+ T cells, CD8+ T cells and fibroblasts of SKCM with lymph node metastasis." (PMID 37670976, 2023). "In early-stage cancer, CD8+ cells and the CD8+/CD4+ ratio were also found to be significantly elevated in patients without lymph node metastases." (PMID 37109686, 2023). "The expression of immunohistochemical markers (PD-L1, PD-1, CD4, CD8, FOXP3) was correlated with retrospective clinic pathological parameters (lymph node metastasis, distant metastasis, lymph node metastasis during follow-up, disease progression, disease-specific death)." (PMID 37932810, 2023). "We found that the CD4+/CD8+ ratio was significantly higher in patients with axillary lymph node metastasis (1.54 ± 0.42) than in patients without axillary lymph node metastasis (1.29 ± 0.43) (P=0.021)." (PMID 36033472, 2022). "CCL5 affected tumor progression through CCR5, and the T-cell-related immune pathway may be the main pathway; the CD4+/CD8+, CCR5+/CD4+ and Treg/CCR5+ cell ratios were significantly increased in the lymph node metastasis group." (PMID 36033472, 2022). "We used Wilcoxon’s test to find that activated T cells CD4 memory and T cells follicular helper showed significant differences in lymph node metastasis and non-metastasis groups." (PMID 35646079, 2022). "Th17 cells are a subset of CD4 + T cells, and high levels of tumor-infiltrating Th17 cells are correlated with lymph node metastases and have a negative impact on the postoperative survival of cancer patients." (PMID 32873319, 2020). "High infiltration of CD4+ T lymphocytes correlated with well-differentiated classification (P = 0.028) and negative for lymph node metastasis (P = 0.009)." (PMID 29732001, 2018). "The results showed that an increase in the CD4+CD25+Foxp3+(Treg)/CCR5+ cell ratio was closely related to the invasiveness of tumors: the Treg/CCR5 ratio in the lymph node metastasis group and nonmetastasis group was 0.028 ± 0.007 and 0.024 ± 0.003, respectively, P = 0.035." (PMID 36033472, 2022). "There are a negative correlation for CD4+ T‐cell counts and positive correlation for percentages of CD8+ HLA‐DR/CD8+ T cell and CD8+ CD38+/CD8+ T cells with the lymph node metastasis." (PMID 32459060, 2020). "There are no clear relationships among levels of memory CD4+/CD4+ T cells, naïve CD4+/CD4+ T cells, CD8+ T cells, or the CD4+/CD8+ ratio and age, stage, tumor stage, and lymph node metastasis differentiation." (PMID 32459060, 2020). "The results revealed that the increasing CD4+CD25+FOXP3+ Treg percentage correlated closely with the TNM staging and lymph node metastasis status (P < 0.05), while no such relationship was observed with the sex or pathological tumour type (P > 0.05)." (PMID 28253320, 2017). "Despite no relevant association of PD-1 expression with tumor size (data not shown), patients with lymph node metastasis (N+) had significantly higher PD-1 expression on CD4+ Tconv, Treg cells and CD8+ T cells compared to patients without lymph node metastasis (N-)." (PMID 32987956, 2020).
B-cell lymphoma (78 papers, 2010 to 2026). "CD4+ follicular helper T cells (Tfh) are essential in the formation of the GC, which is the histological site where most B-cell lymphomas, including those associated with EBV, are generated." (PMID 40963636, 2025). "Previous studies have reported that high levels of CD4+ T cells are associated with improved survival outcomes in many malignancies, and mouse models of B–cell lymphoma suggest that CD4+ T cells are key to the establishment of an antitumor microenvironment." (PMID 34610582, 2021). "Investigators have found that co-injection of MSCs with neoplastic (A20) B cells promotes B cell lymphoma growth in the lacrimal glands of immunocompetent mice and were associated with marked increased in CD4+ forkhead box P3 (FoxP3) + T cells and myeloid-derived suppressor cells." (PMID 30101129, 2018). "B-cell lymphomas, including Burkitt lymphoma (BL), diffuse large B-cell lymphoma (DLBCL), and follicular lymphoma (FL), evade CD4+ T-cell immunity through novel HLA class II-associated immunosuppressive mechanisms." (PMID 40801653, 2025). "This study reveals a critical immune evasion mechanism in B-cell lymphoma (BL), where tumor-derived factors impair CD4+ T-cell recognition by disrupting HLA class II-mediated antigen presentation." (PMID 40801653, 2025). "This study identifies key deficiencies in HLA class II protein-mediated antigen presentation by B-cell lymphoma cells and implicates tumor-derived factors in disrupting CD4+ T-cell activation." (PMID 40801653, 2025). "In murine B cell lymphoma models, which allow for in vitro (CD4 DO-11.10 cells) and in vivo functional examination of defective antigen presentation, CD74 appear to be the main “target” of IRF8 effects." (PMID 38996030, 2024). "The two fractions were then offered to the C3.g7 APC line (B-cell lymphoma expressing I-Ag7) for antigen presentation to 6.9HIP-reactive, I-Ag7-restricted CD4 T-cell hybridomas." (PMID 38455055, 2024). "The critical role of CD4+ Th cells was also reported with patient-derived xenograft (PDX) in several histologic subtypes of B-cell lymphoma." (PMID 37297008, 2023). "In particular, we have previously shown that CD4+ CAR T cells are poorly effective in a model of Myc-driven B-cell lymphoma (Eμ-myc), whereas CD8+ CAR T cells (CAR8 T cells) readily induced tumor regression." (PMID 37248395, 2023). "In a clinical trial, 32 patients of non-Hodgkin B-cell lymphoma treated with CD19 CAR-T cells in a 1:1 ratio of CD8+/CD4+ T cells exhibit long duration of CAR-T cells and have slow disease progression." (PMID 38037114, 2023). "Preclinical studies in xenogeneic animal models of B-cell lymphoma have shown that CART19 cells manufactured from CD4 and CD8 TN and TCM cells have improved antitumor effect compared with those CART derived from more differentiated T-cell subsets." (PMID 35874685, 2022). "In fact, preclinical studies in xenogeneic animal models of B-cell lymphoma have shown increased antitumor effect of CAR19 T cells with a defined composition of CD4:CD8 ratios (e.g., ratio 1:1)." (PMID 35874685, 2022). "A similar combination therapy with radiotherapy and TLR stimulation was applied in patients with low-grade B cell lymphoma which develop specific CD4+ T cell response against a tumor." (PMID 31886298, 2019). "Taken together, these results indicate that PD-1 and LAG-3 cooperatively mediate the functional exhaustion of CD4+ and CD8+ T cells and are associated with the development of B-cell lymphoma in BLV-infected cattle." (PMID 29914540, 2018). "HIV+ patients with B-cell lymphoma have shown a loss of EBV-specific mono- and multifunctional CD4+ and CD8+ T cells." (PMID 30337929, 2018). "Herein, we report a recessive partial TYK2 deficiency in two siblings who presented with T-cell lymphopenia characterized by low naïve CD4+ T-cell counts and who developed Epstein-Barr virus (EBV)-associated B-cell lymphoma." (PMID 29725107, 2018).